MDK (midkine)
Diseases named in the same sentence as MDK in open-access papers (continued):
Sharing a sentence is not in itself a finding about the gene and the disease.
mesothelioma (2 papers, 2017 to 2022). A usually malignant and aggressive neoplasm of the mesothelium which is often associated with exposure to asbestos. "In contrast, elevated baseline levels of midkine were independently associated with a poor prognosis of mesothelioma patients after adjusting for the stage, the histological subtypes and treatment schedules (HR = 1.84; 95% CI: 1.09-3.09) (p = 0.022)." (PMID 28335760, 2017). "In contrast, high serum midkine levels were independently associated with poor prognosis in mesothelioma (HR = 1.84; 95% CI: 1.09-3.09) (p = 0.022)." (PMID 28335760, 2017). "We then investigated possible prognostic values of serum mesothelin and midkine in patients with mesothelioma." (PMID 28335760, 2017). "Nevertheless, the AUC of combined serum mesothelin and midkine to distinguish mesothelioma patients from benign asbestos pleurisy patients was significantly higher than that of midkine (p = 0.0329)." (PMID 28335760, 2017). "The combination of both mesothelin and midkine showed a higher sensitivity than mesothelin or midkine alone, but specificity of the combination was similar to that of midkine except comparison of mesothelioma versus benign pleural diseases." (PMID 28335760, 2017). "The AUC of the combination of the biomarkers was higher than that of midkine to distinguish patients with mesothelioma from all other patients in the study (p = 0.0002)." (PMID 28335760, 2017). "In the current study, we compared the diagnostic ability of mesothelin and midkine to differentiate mesothelioma from other pleural disease, and we firstly demonstrated to our knowledge that serum midkine levels possessed a prognostic value in mesothelioma." (PMID 28335760, 2017). "Sensitivity and specificity of midkine were 61.1 and 41.1%, 61.1 and 48.1%, and 61.1 and 75% to distinguish mesothelioma from metastatic cancers to pleura, other benign pleural diseases and benign asbestos pleurisy, respectively." (PMID 28335760, 2017). "Midkine is thus a novel biomarker for mesothelioma and has a different clinical value from mesothelin." (PMID 28335760, 2017). "An inhibitor of midkine has recently been described as a potential mesothelioma treatment." (PMID 36016386, 2022). "We further investigated possible diagnostic values of mesothelin and midkine using ROC curve analyses to differentiate mesothelioma from non-mesothelioma patients." (PMID 28335760, 2017). "The study did not however show detailed data of midkine by itself in term of the diagnostic and prognostic values and the present study in fact firstly delineated the value of midkine as a biomarker in mesothelioma." (PMID 28335760, 2017). "In contrast, midkine was a useful marker for predicting prognosis of mesothelioma patients." (PMID 28335760, 2017). "The AUC of serum mesothelin to distinguish patients with mesothelioma from those with metastatic cancers to pleura was significantly higher than that of serum midkine (p = 0.0330) but was not different from that of combination of both mesothelin and midkine (p = 0.0738)." (PMID 28335760, 2017). "Mesothelin therefore differentiated mesothelioma from non-mesothelioma diseases, but midkine had a limited value only to discriminate mesothelioma from benign asbestos pleurisy." (PMID 28335760, 2017). "Serum midkine levels also tended to increase according to the stage progress (P = 0.059), but the levels were not related to the histological types of mesothelioma (P = 0.501)." (PMID 28335760, 2017). "We also examined the sensitivity, specificity, positive and negative predictive values of mesothelin, midkine, and the combination of the biomarkers to differentiate patients of mesothelioma from other patients." (PMID 28335760, 2017). "In contrast, midkine has not yet been studied for a potential role in either the diagnosis or the prognosis of mesothelioma." (PMID 28335760, 2017).
mesothelioma (continued). "Our results also indicated that neither serum mesothelin or midkine discriminated mesothelioma at stage I or II from benign asbestos pleurisy." (PMID 28335760, 2017). "We showed that midkine was expressed in human mesothelioma cell lines (data not shown), but have not yet analyzed midkine levels in the specimens because precise estimation of tumor ratios in respective clinical samples is required." (PMID 28335760, 2017). "Baseline serum mesothelin and midkine levels at the diagnosis were not related to the chemotherapy responses of mesothelioma patients." (PMID 28335760, 2017). "In contrast, serum midkine levels of mesothelioma patients were not different from those of patients with metastatic cancers to pleura, benign pleural diseases or pleural diseases other than mesothelioma, but were greater than those with benign asbestos pleurisy patients." (PMID 28335760, 2017).
Obesity (2 papers, 2019 to 2025). Accumulation of substantial excess body fat. "Therefore, it has been suggested that MDK is a novel adipocyte-secreted factor associated with obesity." (PMID 31648221, 2019). "In contrast, MDK is highly expressed in several pathological conditions, including autoimmunity, dyslipidemia, atherosclerosis, obesity, and most important for this review, many cancers." (PMID 40429950, 2025). "Another study has demonstrated that MDK can be secreted by adipose progenitor cells, which are expanded in obesity, to recruit monocytes to the resident tissue." (PMID 40429950, 2025). "Obesity and estrogen signaling, a known critical driver of women’s cancer, further elevate the levels of MDK." (PMID 40429950, 2025). "Serum MDK concentrations were found to be elevated in adults with obesity." (PMID 31648221, 2019). "Interestingly, a set of studies has indicated that MDK may be involved in or promoted by obesity." (PMID 40429950, 2025). "Furthermore, MDK concentrations were not significantly different in conditions involving extremes of adiposity–obesity or anorexia nervosa." (PMID 31648221, 2019).
osteoporosis (2 papers, 2023 to 2025). A condition of reduced bone mass, with decreased cortical thickness and a decrease in the number and size of the trabeculae of cancellous bone (but normal chemical composition), resulting in increased fracture incidence. "In this study, we observed significantly elevated serum levels of midkine (MDK) in patients with postmenopausal osteoporosis and in ovariectomized mice, based on clinical data and animal experiments." (PMID 41674663, 2025). "Therefore, possible osteoclast-stimulating factors released from mast cells that could be involved in osteoporosis development might be Midkine and/or CXCL-10, which needs to be verified in future studies." (PMID 37298085, 2023).
pancreatic ductal adenocarcinoma (2 papers, 2013 to 2025). An infiltrating adenocarcinoma that arises from the epithelial cells of the pancreas. "MDK, which originated from pancreatic ductal adenocarcinoma cells, exerted deleterious effects on paraneoplastic beta cells by binding to the SDC4 receptor on the beta cell surface and subsequently downregulating the Ras signaling pathway, thereby impairing insulin production and secretion." (PMID 40709672, 2025).
rectal cancer (2 papers, 2012 to 2020). A primary or metastatic malignant neoplasm that affects the rectum. "In this respect, higher baseline midkine expression in rectal mucosa together with a direct midkine association with disease progression might contribute to this feature of rectal cancers." (PMID 22562257, 2012). "High midkine expression in noncancerous rectal mucosa might contribute to, a characteristic for rectal cancers, higher incidence of local recurrence." (PMID 22562257, 2012).
renal fibrosis (2 papers, 2024 to 2025). A final common manifestation of a wide variety of chronic kidney diseases characterized by glomerulosclerosis and tubulointerstitial fibrosis. "Previous studies have identified ANGPTL4 and MDK as key factors in inducing CAFs transformation and mediating renal fibrosis." (PMID 41383622, 2025). "Next, we want to specifically elucidate the roles of MDK expressed by ECs in EndMT of renal fibrosis." (PMID 38714800, 2024). "To study the functional relevance of MDK in renal fibrosis, we employed Mdk−/− mice for further investigation." (PMID 38714800, 2024). "This study focuses on how endothelial cells contribute to ECM accumulation of renal fibrosis and suggests that MDK promotes ACTA2 expression by stabilizing the C/EBPβ protein." (PMID 38714800, 2024). "In conclusion, our study provides a mechanistic link between the induction of EndMT by TGF-β and MDK, which suggests that blocking MDK provides potential therapeutic strategies for renal fibrosis." (PMID 38714800, 2024). "Conclusively, we proved that MDK increasingly expressed by CD31+ACTA2+ ECs during EndMT may be involved in the development of renal fibrosis." (PMID 38714800, 2024). "We also demonstrate that blocking MDK inhibits EndMT and reverses renal fibrosis." (PMID 38714800, 2024). "Our work suggests that blocking MDK provides a potential therapeutic strategy for renal fibrosis." (PMID 38714800, 2024). "Therefore, ECs possibly produced the greatest level of MDK in renal fibrosis." (PMID 38714800, 2024). "Altogether, our study substantiates the involvement of MDK in mediating TGF-β-induced EndMT and renal fibrosis through stabilizing C/EBPβ, which is physiologically significant for emergence of CD31+ACTA2+ECs." (PMID 38714800, 2024). "We illustrate a new mechanism linking MDK and C/EBPβ in a fundamental TGF-β-induced EndMT process and renal fibrosis." (PMID 38714800, 2024). "MDK mainly expressed by CD31+ACTA2+ ECs during partial EndMT contributes greatly to myofibroblasts and promotes renal fibrosis through stabilizing C/EBPβ, which subsequently activate ACTA2 expression by directly targeting its promoter region." (PMID 38714800, 2024).
thyroid (2 papers, 2016 to 2024). "The results of the presented study demonstrate that both SMK and NMK might be the indicators of highly malignant/suspicious thyroid cytopathology, suggesting that midkine might serve as a novel biomarker in conjunction with the cytopathological results in preoperative assessment of thyroid nodules." (PMID 27446208, 2016).
viral diseases (2 papers, 2018 to 2025). "Furthermore, cell surface NCL ligands, such as midkine and lactoferrin, have similar effects during viral infection." (PMID 30339712, 2018).
actinic keratosis (1 paper, 2022). A precancerous lesion of the skin composed of atypical keratinocytes. "We examined the effect of MDK on fibroblasts by investigating the expression of MDK and VIM (a general marker of fibroblasts) in normal skin and actinic keratosis (AK) samples." (PMID 36438481, 2022).
alveolar soft tissue sarcoma (1 paper, 2025). "Additionally, both tumors and PTCs of alveolar soft tissue sarcoma (ASPS) highly expressed PSAP, MDK, and HIF1A, known to be related to the differentiation of mesenchymal stem cells." (PMID 40054460, 2025).
autoimmune encephalitis (1 paper, 2010). Inflammation of the brain secondary to an immune response triggered by the body itself. "An aptamer, which has midkine inhibitory activity and inhibits development of experimental autoimmune encephalitis, was also found using the method." (PMID 20565917, 2010).
brain trauma (1 paper, 2025). "Elevated MDK expression has also been noted in response to neuroinflammatory conditions and after exposure to substances of abuse such as amphetamines, alcohol, and opioids, as well as following various types of brain trauma including ischemia." (PMID 40500394, 2025).
cervical tumors (1 paper, 2022). "We found that downregulated genes in PR patient, such as IL17D, MDK and GNRH1, which are known for their role in the innate immune system, are unfavorable prognostic factors highly expressed in primary cervical tumors and across cancers." (PMID 36171464, 2022).
chondrosarcoma (1 paper, 2024). A malignant cartilaginous matrix-producing mesenchymal neoplasm arising from the bone and soft tissue. "In chondrosarcomas (CSs), DAC treatment has been shown to hypomethylate Satellite 1 and L1 and overexpress genes like Sox-2 and midkine (MDK), leading to increased tumor invasiveness in some models while inhibiting growth in others." (PMID 39590345, 2024).
chordoma (1 paper, 2022). Chordomas are rare malignant tumors arising from embryonic remnants of the notochord in axial skeleton. "The increase in the levels of PLCD and MDK was corroborated using chordoma cell lines by western blotting." (PMID 36059685, 2022).
chorioamnionitis (1 paper, 2016). A morphologic finding indicating inflammation of the fetal sac membranes. "Interestingly, AF MDK concentrations in term pregnancies complicated by chorioamnionitis were lower than in healthy term pregnancies in the absence of labor (1.12 ± 0.24 ng/ml vs. 3.61 ± 1.51, P = 0.015)." (PMID 27089523, 2016). "Similar to MDK, AF PTN concentrations in term pregnancies complicated by chorioamnionitis were lower than in healthy term pregnancies in the absence of labor (3.47 ± 0.79 ng/ml vs. 6.30 ± 1.00 ng/ml, P = 0.01)." (PMID 27089523, 2016). "Both AF MDK and PTN concentrations were lower in pregnancies complicated by chorioamnionitis than in healthy pregnancies." (PMID 27089523, 2016). "Both MDK and PTN concentrations were found to be lower in pregnancies that were complicated by chorioamnionitis at term, raising the possibility that these growth factors might be useful as markers for infection." (PMID 27089523, 2016). "Both MDK and PTN levels were found to be lower in pregnancies complicated by chorioamnionitis, suggesting that these growth factors might be used clinically as markers for infection." (PMID 27089523, 2016). "Interestingly, both MDK and PTN concentrations were lower in term samples from pregnancies complicated by chorioamnionitis than in those from healthy pregnancies, suggesting that infection either decreases the expression or accelerates the degradation of these growth factors." (PMID 27089523, 2016).
chronic lymphocytic leukemia (1 paper, 2017). "Elevation of midkine, produced by normal and malignant B-cells, tumor and stromal cells, was also reported in other B-cell malignancies such as chronic lymphocytic leukemia and lymphomas." (PMID 29050213, 2017).
cognitive decline (1 paper, 2026). "This suggests that MDK is a crucial mediator of microglial pro‐inflammatory activation and enhanced phagocytic function, offering insights into the neurotoxic effects observed in various pathologies, including AKI‐related cognitive decline." (PMID 41276912, 2026).
colitis (1 paper, 2017). Inflammation of the colon. "In an experimental colitis model, a well-established model for UC, midkine was abundantly expressed in fibroblasts of the mucosal and submucosal layers of the rat distal colon." (PMID 27903979, 2017).
desmoid tumor (1 paper, 2012). A desmoid tumor (DT) is a benign, locally invasive soft tissue tumor associated with a high recurrence rate but with no metastatic potential. "It is worth mentioning that midkine has recently been suggested as the recurrence marker for desmoid tumors, monoclonal neoplasms that may occur as a part of familial adenomatosis polyposis." (PMID 22562257, 2012).
diabetic kidney disease (1 paper, 2025). Progressive kidney disorder caused by vascular damage to the glomerular capillaries, in patients with diabetes mellitus. "In a diabetic kidney disease (DKD) model, antisense oligonucleotides (ODNs) targeting MDK significantly improved renal function and reduced tissue damage by suppressing MDK expression." (PMID 40500394, 2025).
gastric ulcer (1 paper, 2008). An ulcerated lesion in the mucosal surface of the stomach. "Rebamipide, a mucoprotective drug used for the treatment of gastric ulcers, has been shown to upregulate MDK expression in rat gastric mucosal cells." (PMID 18275606, 2008).
glaucoma (1 paper, 2024). Increased pressure in the eyeball due to obstruction of the outflow of aqueous humor. "Three hub genes, CD40LG, TEK, and MDK, were validated as potential diagnostic biomarkers for high-risk glaucoma patients, showing increased expression in the NMDA-induced excitotoxicity model." (PMID 38694874, 2024). "The inquiry about MDK and its potential clinical translation or treatment significance for glaucoma appeared to be an under-explored area in the highlighted articles." (PMID 38694874, 2024).
growth disorders (1 paper, 2019). "Because of this possible role of MDK in normal childhood growth, we were particularly interested to see whether MDK might be altered in some children with growth disorders." (PMID 31648221, 2019).
head and neck cancer (1 paper, 2026). A primary or metastatic malignant neoplasm affecting the head and neck. "MDK‐TSPAN1 has been shown to promote tumorigenesis and chemoresistance in head and neck cancer." (PMID 41362277, 2026).
hepatoblastoma (1 paper, 2025). Hepatoblastoma (HB) is a malignant hepatic tumor and is the most common pediatric liver cancer. "Using an in vitro co-culture system, the study demonstrated that hepatoblastoma cells can induce a pro-fibrotic shift in macrophages, potentially mediated by MDK." (PMID 40684183, 2025). "This study uncovered a WNT–MDK axis that drives immune evasion in poorly differentiated hepatoblastoma, thereby providing a mechanistic basis for the immune-cold phenotype observed in aggressive tumors and highlighting MDK as a promising therapeutic target to overcome immune resistance." (PMID 40684183, 2025). "As a growth factor, MDK may also promote the survival, proliferation, and metastasis of hepatoblastoma cells, which has been reported in other types of cancers." (PMID 40684183, 2025).
Hypervolemia (1 paper, 2022). An increase in the amount of intravascular fluid, particularly in the volume of the circulating blood. "Thus, for dialysis patients inadequate periprocedural midkine upregulation is linked with hypervolemia and associates with cardiovascular events." (PMID 35211826, 2022). "Thus, vascular stress caused by chronic hypervolemia may suppress midkine release by endothelial cells or, conversely, a diminished midkine release may be causatively linked with a failure to mobilize interstitial fluid." (PMID 35211826, 2022).
Infertility (1 paper, 2019). "MDK knockout in mice has little phenotypic effect but double knockout of MDK and pleiotrophin impairs postnatal growth and causes infertility." (PMID 31648221, 2019).
ischemic disease (1 paper, 2022). Lack of blood supply to an area of the body, resulting in impairment of tissue oxygenation. "The heparin-binding growth factor midkine stimulates neo-angiogenesis in ischemic diseases, coordinates neutrophil influx, and raises blood pressure through stimulated angiotensin synthesis." (PMID 35211826, 2022).
keratinocyte carcinoma (1 paper, 2025). A skin cancer arising from the keratin-producing cells of the epidermis. "In human skin, midkine overexpression is observed in keratinocyte cancers and can stimulate keratinocyte proliferation in vitro." (PMID 40319033, 2025).
kidney damage (1 paper, 2020). "There was no data available on proteinuria and albuminuria, so we were unable to determine if serum MDK was associated with these early indicators of kidney damage." (PMID 32879333, 2020).
leptomeningeal metastases (1 paper, 2025). "Similarly, while MDK expression was negligible in the immune cells of normal CSF, both macrophages and type 1 conventional dendritic cells exhibited enhanced MDK expression in the CSF of patients with leptomeningeal metastases." (PMID 40429950, 2025).
lung diseases (1 paper, 2025). "In lung diseases, MDK is reported to be expressed in small airways, type II pneumocytes, and alveolar macrophages in COPD, as well as in the sputum of patients with ventilator-associated pneumonia caused by S. aureus." (PMID 40943439, 2025). "However, the specific role of MDK in lung diseases remains unclear." (PMID 40943439, 2025).